RNU6-705P (RNA, U6 small nuclear 705, pseudogene)
Gene: Small nuclear RNA gene on chromosome 5 (181,301,967 to 181,302,070, forward strand). Ensembl gene ENSG00000222533.
Homologues: Orthologues: macaque U6 (90% identical), pig U6 (84% identical), pig U6 (78% identical), dog U6 (77% identical). Paralogues in human: RNU6-1076P (99% identical), RNU6-1100P (99% identical), RNU6-1118P (99% identical), RNU6-1217P (99% identical), RNU6-355P (99% identical), RNU6-447P (99% identical), RNU6-785P (99% identical), RNU6-791P (99% identical), RNU6-860P (99% identical), U6 (99% identical), RNU6-1054P (98% identical), RNU6-1199P (98% identical), and 1290 more.